CRLF1 (cytokine receptor like factor 1)
Diseases named in the same sentence as CRLF1 in open-access papers (continued):
Sharing a sentence is not in itself a finding about the gene and the disease.
renal dysplasia (1 paper, 2015). Renal dysplasia is a form of renal malformation in which the kidney(s) are present but their development is abnormal and incomplete. "A case of renal dysplasia associated with cold sweating syndrome and potential deficiency of CLCF-1/CRLF-1 has been reported." (PMID 26146641, 2015).
skin cancer (1 paper, 2009). "Noticeably among the cytokine receptor-like factor 1 and 3 (Crlf1, Crlf3) that belong to the same family, Crlf3 has been found to be up-regulated in skin cancer." (PMID 19799787, 2009).
tumor (13 papers, 2018 to 2026). "Remarkably, binding-defective CRLF1 variants promoted tumor-specific pyroptosis and chemosensitization by impairing the AKT-SIN1 interaction." (PMID 39256356, 2024). "By using loss-of-function and gain-of-function assays, we found that CRLF1 not only increased cell migration and invasion in vitro but also promoted tumor growth both in vitro and in vivo." (PMID 29515111, 2018). "To explore whether these variants exert their functions in a tumor-specific or CRLF1 expression level-dependent manner, we compared CRLF1 expression levels in IOSE-80 (a normal ovarian epithelial cell line) with A2780 and CaoV3 cells." (PMID 39256356, 2024). "Interestingly, the overexpression of binding-defective CRLF1 variants effectively increased pyroptosis in a tumor-specific manner." (PMID 39256356, 2024). "However, high CRLF1 expression levels were associated with tumor size, extrathyroidal extension, T stages, N stages, and clinical stages (P < 0.05)." (PMID 29515111, 2018). "In vitro and in vivo investigations illustrated that silencing CRLF1 significantly suppressed PCa cell growth, invasion, and tumor progression, while enhancing apoptosis." (PMID 42122189, 2026). "At the mechanistic level, CRLF1 facilitates tumor progression by modulating COMP to activate the FAK/PI3K/AKT signaling cascade." (PMID 42122189, 2026). "CRLF1 increased cell migration and invasion in vitro and promoted growth tumours in vitro and in vivo." (PMID 35055176, 2022). "Downregulation of CRLF1 in cancer cells led to a decrease in tumor growth rate and decreased final mean tumor volume compared with control cells." (PMID 34211976, 2021). "Knocking down MYH9 in CRLF1-overexpressing IHH4 cells markedly lowered tumor formation with significantly smaller volumes of tumors reported compared with the cells transfected with siNC." (PMID 32982961, 2020). "Altogether, these results imply that knocking down MYH9 reverses CRLF1-induced tumor metastasis and EMT in PTC cells." (PMID 32982961, 2020). "Our data showed that ectopic expression of CRLF1 significantly increased cell growth and colony formation ability in vitro and induced tumor formation in nude mice in vivo." (PMID 29515111, 2018). "Several factors, including extrathyroidal extension, multifocality, T stage, N stage, M stage, tumor-node-metastasis (TNM) stage, and CRLF1 expression, were significantly associated with DFS rates by univariate Cox regression analysis." (PMID 29515111, 2018). "Moreover, the expression level of CRLF1 was down-regulated in tumor samples compared with normal samples (P = 4.1e−10)." (PMID 35748788, 2022). "More importantly, CRLF1 is involved in the regulation of tumor progression." (PMID 34656128, 2021). "In addition, western blot analysis and immunohistochemical staining showed a reduction in CRLF1 expression in the tumor tissues of the mouse model." (PMID 34656128, 2021). "Further, we also examined whether knocking down MYH9 in CRLF1-overexpressing TPC1 cells would affect tumor proliferation and colony formation." (PMID 32982961, 2020). "Next, we evaluated the effects of CRLF1 on tumor growth in vivo." (PMID 29515111, 2018). "First, CRLF1 expression was higher in PTC tumor tissues than that in matched non-tumor tissues." (PMID 29515111, 2018). "In addition, CRLF1 silencing suppressed tumor growth in xenograft models." (PMID 39256356, 2024). "Next, we evaluated whether MYH9 reverses CRLF1-induced tumor proliferation in vivo." (PMID 32982961, 2020). "Among them, TDGF1, and GRP were up-regulated in tumor samples, while NRG1, CRLF1, and IL20RB were down-regulated in tumor samples." (PMID 35748788, 2022). "We demonstrated that CRLF1 interacts with MYH9, promoting tumor proliferation and metastasis by activating ERK/ETV4; therefore, we provide a prospective therapeutic target for the treatment of PTC." (PMID 32982961, 2020).
tumor (continued). "High genomic alterations in zesto lesions were inversely correlated with putative tumor suppressor genes (MTUS2, DLGAP3, RTN1, CRLF1, SLC12A5, and PDIA2) and positively correlated with APOBEC mutagenesis (APOBEC3C, APOBEC3G, APOBEC3B, and APOBEC3F) and hypoxia-related gene signatures." (PMID 40319462, 2025). "Next, the rescue experiments confirmed that interfering with MYH9 significantly reduces tumor proliferation on CRLF1-overexpressing PTC cells but not in vector-expressing cells, in vitro, and in vivo." (PMID 32982961, 2020). "Interestingly, CRLF1 does not require CLCF1 or GP130 in this novel role, although the studies were performed only in a tumour-derived cell model system." (PMID 35055176, 2022).
cancer (5 papers, 2018 to 2026). A tumor composed of atypical neoplastic, often pleomorphic cells that invade other tissues. "Previous studies have demonstrated CRLF1 involves in cancer cells proliferation, neuronal development, and immune regulation." (PMID 39256356, 2024). "CRLF1 is verified to be involved in regulating malignant cancer cell proliferation and invasion, which can affect signaling pathways (such as MAPK/ERK and Akt/PI3K) and modulate the immune and nervous systems maturity during fetal development." (PMID 32968155, 2020). "Importantly, suppressing COMP counteracted the cancer-promoting effects triggered by CRLF1 overexpression." (PMID 42122189, 2026). "Targeting CRLF1 might enable AKT inhibition with greater specificity towards cancer cells." (PMID 39256356, 2024).
genetic diseases (3 papers, 2020 to 2025). "Additionally, studies on other gene mutations, such as CRLF1, have shown how early diagnosis can significantly improve patient outcomes, particularly in the management of rare genetic diseases." (PMID 39948613, 2025). "Eventually, data from human genetic disorders identified cytokine receptor-like factor 1 (CRLF1)/cardiotrophin-like cytokine factor 1 (CLCF1) as cholinergic differentiation factor in human sweat glands." (PMID 32930881, 2020). "The mutational inactivation of CRLF1 and leukemia inhibitory factor receptor (LIFRβ) in human genetic diseases identified CRLF1/CLCF1 to be essential for cholinergic differentiation of sweat gland innervation." (PMID 32930881, 2020).
infection (1 paper, 2023). The state of being infected such as from the introduction of a foreign agent such as serum, vaccine, antigenic substance or organism. "In response to infection, four interleukins (IL1A, IL1B, IL8 and IL16), their receptors (IL1 receptor like 1, IL1 receptor 2, IFN-lambda receptor 1, cytokine receptor like factor 1) and two acute phase proteins (Serum amyloid A 1 and 2) were differentially expressed." (PMID 38179419, 2023).
CRLF1 also shares sentences with these, for which no sentence is quoted: avascular necrosis (1 paper); cardiofaciocutaneous syndrome (1); CHARGE syndrome (1); chondrosarcoma (1); cold-induced sweating syndrome type 1 (1); fibrosis (1); heart failure (1); hepatoblastoma (1); Kyphoscoliosis (1); lipoblastoma (1); lung adenocarcinoma (1); lung disease (1); Moebius syndrome (1); neurological disorders (1); pleomorphic adenomas of the salivary gland (1); prostate carcinoma (1).